TXNL4B (thioredoxin like 4B)
Description:
Essential role in pre-mRNA splicing. Required in cell cycle progression for S/G(2) transition.
Synonyms: DIM2; DLP; FLJ20511
Tractability: Small molecule: a structure with a bound ligand is known. PROTAC: ubiquitination databases record sites on it; its protein half-life has been measured.
Gene: Protein-coding gene on chromosome 16 (72,084,854 to 72,094,431, reverse strand). Ensembl gene ENSG00000140830.
Subcellular location: Nucleus
Subcellular location (Human Protein Atlas): Nucleoplasm; Cytosol
Gene Ontology:
Molecular function: protein binding
Biological process: spliceosomal tri-snRNP complex assembly; spliceosome conformational change to release U4 (or U4atac) and U1 (or U11); mRNA splicing, via spliceosome
Cellular component: nucleoplasm; U12-type precatalytic spliceosome; spliceosomal complex; U4/U6 x U5 tri-snRNP complex; U4atac/U6atac x U5 tri-snRNP complex; U5 snRNP; nucleus
Genetic constraint (gnomAD): Loss-of-function variants: 12 observed, 12.59 expected, observed/expected ratio (o/e) 0.95, 90% interval 0.61 to 1.53. The upper end of that interval is the gene's LOEUF score, 1.53, which puts it in group 6 of 6, group 1 being the genes least tolerant of losing a copy. Missense variants: 201 observed, 169.23 expected, observed/expected ratio (o/e) 1.19, 90% interval 1.06 to 1.34. Synonymous variants: 55 observed, 56.46 expected, observed/expected ratio (o/e) 0.97, 90% interval 0.78 to 1.22.
Homologues: Orthologues: chimpanzee TXNL4B (100% identical), rabbit TXNL4B (98% identical), rat Txnl4b (98% identical), mouse Txnl4b (97% identical), pig TXNL4B (97% identical), guinea pig TXNL4B (96% identical), tropical clawed frog txnl4b (87% identical), zebrafish txnl4b (84% identical), macaque TXNL4B (66% identical), dog TXNL4B (63% identical). Paralogues in human: TXNL4A (36% identical).
Diseases named in the same sentence as TXNL4B in open-access papers:
TXNL4B is named in the same sentence as 15 diseases in open-access papers, as found by Europe PMC text mining. Sharing a sentence is not in itself a finding about the gene and the disease. The quoted sentences say what the papers report.
fibroids (1 paper, 2025). "Within these 15 pairs, there were four unique genes (NQO1, AC004889.1, TXNL4B, and GGT1), and all four of those genes have not been previously associated with fibroids in the GWAS catalog and were significant only in the African ancestry analysis." (PMID 40050615, 2025).
gastric cancer (1 paper, 2009). A primary or metastatic malignant neoplasm involving the stomach. "The genes PLA2G4A, BMP5, MMP6, KNNMB4 and DYM were candidates for the GP202 gastric cancer cell line and the genes TXNL4B, FOXK1, PTPRJ, and SNN were candidates for the IPA220 gastric cancer cell line." (PMID 19563644, 2009).
lung carcinoma (1 paper, 2023). "Here, we demonstrated that TXNL4B promotes radioresistance in lung cancer cells, whereas the silence of TXNL4B expression reverses the cancer cell resistance status postradiation." (PMID 37168687, 2023). "Here, we reported that the spliceosomal protein thioredoxin‐like 4B (TXNL4B) is highly expressed in lung tissues from lung cancer patients with radiotherapy." (PMID 37168687, 2023). "WB detection further confirmed that lung cancer tissues of patients post‐radiotherapy had an overexpression of TXNL4B expression." (PMID 37168687, 2023). "Nude mice were divided into two groups, one injected with NT‐shRNA‐A549 cells to establish lung cancers, whereas another group injected with TXNL4B‐knockdown cells." (PMID 37168687, 2023). "First of all, lung cancer tissues from patients who received radiotherapy were collected, and the TXNL4B expression was detected." (PMID 37168687, 2023). "Based on these findings, it would be potential for developing precise and effective radiotherapy targets in lung cancer cells through blocking TXNL4B‐mediated PRP3 activity and translocation in clinics." (PMID 37168687, 2023). "TXNL4B expression was detected in the lung cancer tissues of patients who received radiotherapy." (PMID 37168687, 2023). "Further study showed that after knock‐downing TXNL4B expression, lung cancer cells obtained aggravation ability for apoptosis postradiation, which raises the hypothesis that TXNL4B might involve in the regulation of lung cancer radioresistance." (PMID 37168687, 2023). "Compared to the normal group, TXNL4B expression was higher in mice with lung cancer." (PMID 37168687, 2023). "We detected the TXNL4B levels in six patients with lung cancer who received radiotherapy." (PMID 37168687, 2023). "Our findings indicate a mechanistic model for the regulation of PRP3 by TXNL4B and the regulation of FANCI splicing isoforms by PRP3 in lung cancer that may have consequences for the susceptibility of this cancer type to radiotherapy." (PMID 37168687, 2023). "The expression of TXNL4B protein and mRNA increased both in lung cancer tissues." (PMID 37168687, 2023). "In lung cancer cell lines, TXNL4B was also overexpressed compared to normal lung cell line." (PMID 37168687, 2023). "Lung cancer cells with TXNL4B knockdown illustrate increased sensitivity to IR." (PMID 37168687, 2023). "In general, above results inform that TXNL4B may involve in the radioresistant because it was overexpressed in lung cancer patients who received radiotherapy as well as in lung cancer line postradiation." (PMID 37168687, 2023). "We suggest that the PRP3, serving as a splicing factor, can be modified by TXNL4B, resulting in promoting G2/M transition, EMT, and DNA repair and contributing to the observed radioresistance of lung cancer through the regulation of FANCI splicing isoforms." (PMID 37168687, 2023). "The 3D structure of TXNL4B and PRP3 can bind together potential, as well as PRP3 plays essential roles in the spliceosome pre‐mRNA splicing, whether PRP3 is involved in the regulation of alternative splicing in lung cancer cells postradiation needed to be evaluated." (PMID 37168687, 2023).
Type II Diabetes (1 paper, 2020). "We found that our false positive associations with genes WFS1, HNF4A, NPHP4, and TXNL4B were reported to be associated with Type II Diabetes in GWAS Catalog while the others were not." (PMID 33206638, 2020).
tumor (3 papers, 2020 to 2024). "We found that, compared with the control group, mice treated with the combination of radiation and TXNL4B knockdown had a trend of tumor regression, whereas, in control group, the tumors kept on growing." (PMID 37168687, 2023).
cancer (1 paper, 2023). A tumor composed of atypical neoplastic, often pleomorphic cells that invade other tissues. "We first found that TXNL4B overexpression or knockdown could influence cell viability in other cancer cells (HepG2 and MDA‐MB‐231)." (PMID 37168687, 2023). "We next evaluated the expression of TXNL4B levels in other various cancers." (PMID 37168687, 2023). "Moreover, it showed that TXNL4B expression was higher in cancer tissues than in adjacent normal tissues." (PMID 37168687, 2023).
TXNL4B also shares sentences with these, for which no sentence is quoted: infection (3 papers); adenocarcinoma of the pancreas (1); colon adenocarcinoma (1); endometriosis (1); esophageal carcinoma (1); malaria (1); metabolic disease (1); sarcoma (1); viral infection (1).